MDM2 (MDM2 proto-oncogene)
Diseases named in the same sentence as MDM2 in open-access papers (continued):
Sharing a sentence is not in itself a finding about the gene and the disease.
tumor (continued). "Both BaseScopeTM and qPCR relative expression analysis demonstrated that MDM2-FL and MDM2-ALT2 isoforms were significantly overexpressed in DDLPS and WDLPS tumor tissue in comparison to NAT." (PMID 39769278, 2024). "The ubiquitin ligase MDM2 reduces c‐Cbl‐mediated STAT5 degradation by competitive binding to STAT5 with c‐Cbl, thereby enhancing tumor‐infiltrating CD8+ T cell‐mediated antitumor immunotherapy (tumor size reduction)." (PMID 38783893, 2024). "In the orthotopic GBM model (3731) amplified with mdm2, RG7112 decreased the rate of tumor progression and prolonged the survival of mice compared to vehicle-treated mice." (PMID 38786726, 2024). "The interaction of MDM2 and circFOXO3 also prevents MDM2 from binding to FOXO3, another tumor suppressor, leading to increased FOXO3 levels and tumor apoptosis." (PMID 39337606, 2024). "The tumor is distinguished by increased expression in the cyclin-dependent kinase 2 (CDK2) and MDM2 genes on chromosome 12." (PMID 39238675, 2024). "The present study reports that a novel MDM2 inhibitor, APG-115, has a potent anti-tumor effect in CLL." (PMID 39144622, 2024). "Both MDM2 and MDMX promote the circulating tumor cells (CTCs) required for the dissemination of xenograft MDA-MB-231 human triple-negative breast cancer (TNBC) cells to travel to the lung to form metastases." (PMID 39766093, 2024). "From dissociated tumors, collagen expression was predominantly from MDM2+ (SA127) or B7H3+ (SA174) tumor cells, suggesting that tumor cells serve as the primary source of collagens in these PDX models." (PMID 39574893, 2024). "Thus, MDM2 inhibitors may boost the tumor immune response by activating DCs." (PMID 39263534, 2024). "MDM2 and MDMX promote circulating tumor cell (CTC) formation and metastasis, and positively correlate with a high expression of CXCR4." (PMID 39766093, 2024). "MDM2 peptides activate CD4+ helper T lymphocytes, and activated helper T lymphocytes secrete cytokines such as IFN-γ, activate CTLs, and directly kill tumor cells via granzyme B92." (PMID 39263534, 2024). "Here, we demonstrate for the first time increased levels of MDM2-FL and MDM2-ALT2 mRNA in WDLPS and DDLPS patient tumor samples in comparison to NAT tissue." (PMID 39769278, 2024). "miR-3174 downregulated the expression of multiple tumor-promoting genes including CD44, MDM2, RHOA, PLAU and CDK6." (PMID 37298284, 2023). "Both molecules (MDM2 and VEGF), responsible for tumour progression, were inhibited by gossypol in a time- and dose-dependent manner (up to 24 h and up to 10 μM)." (PMID 38098026, 2023).
tumor (continued). "Surprisingly, both NTRK fusion and MDM2/CDK4 amplification have been undetected after 5-week treatment of NTRK inhibitor, which was confirmed by the NGS testing of the resected tumor sample." (PMID 36652666, 2023). "A disruptive study demonstrated that MDM2 regulates T cell STAT5 stability, T cell survival, and anti-tumor immunity." (PMID 38203613, 2023). "The expressions of ITPR2, MDM2, KRAS and CDK4 were also highest in the CLDN2+ AT2 cells, and higher in the tumor-derived CLDN2+ AT2 cells than the normal ones." (PMID 37488117, 2023). "Bioinformatics analysis and sequence alignments performed in our laboratory proposed that miR-3174 can target many influential tumor-promoting genes involved in the pathobiology of GBM, including CD44, PLAU, MDM2, CDK6 and RHOA." (PMID 37298284, 2023). "Amplifications of MYC (four cases), MDM2 (two cases), MDM4 (two cases), and several other genes were identified with the Illumina TruSight Tumor 170 panel in a subset of tumors." (PMID 37891989, 2023). "Other tumor suppressors, including E-cadherin 31 and the retinoblastoma protein (RB1) 32 are MDM2 substrates for degradation." (PMID 37496993, 2023). "The tools predicted several tumor-promoting genes as a potential target of miR-3174 including CD44, CDK6, MDM2, RHOA and PLAU." (PMID 37298284, 2023). "Our results indicate that AV25R binds with several proteins known to regulate cell proliferation and tumor progression, such as FECH, MAP11, EGFR, TGFBR1 and MDM2." (PMID 38138609, 2023). "Further, we also demonstrated that miR-3174 downregulates multiple tumor-promoting genes (CD44, MDM2, CDK6, RHOA and PLAU) and all of these have been reported to have an important role in the development of various malignancies, including GBM." (PMID 37298284, 2023). "Its oncogenic or tumor suppressor activities are mainly mediated by ubiquitination of proteins with oncogenic or tumor suppressor functions such as PTEN, MDM2, CNrasGEF, N-Myc and C-Myc, Her3, SAG, AKT, and Ras." (PMID 36918822, 2023). "The analysis of the cfDNA NGS panel before treatment with larotrectinib revealed both TPM3::NTRK1 fusion and MDM2/CDK4 amplification, reliably reflecting the genetic alterations of the original pelvic tumor tissue." (PMID 36652666, 2023). "Several tumor-promoting genes, including MYC and MDM2, are thought to be involved in the disease progression." (PMID 37511127, 2023). "The non-tumour portion of Atf4Δhep livers showed elevated cyclin-D1 (CCND1), mouse double minute 2 homologue (MDM2), connective tissue growth factor (CTGF), and DR5 mRNAs, but reduced FGF21 mRNA." (PMID 36996941, 2023).
tumor (continued). "Positive correlations have resulted importantly between MDM2 and HPV status, cardiovascular diseases, tumor size and tumor stage." (PMID 37081989, 2023). "Our findings suggest that the MDM2 oncogene plays a significant role in HepG2 proliferation, migration, and EMT progression and that the tumor suppressive effect of miR-590-3p in HCC is due to interaction, at least in part, with MDM2." (PMID 37138218, 2023). "Immunohistochemical staining revealed the tumor cells were positive for Vimentin, S-100, CD34 and MDM2." (PMID 37670330, 2023). "AKT also exerts effects over MDM2, BcI2, XIAP and FOXO, all which lead to suppression of tumor cell apoptosis." (PMID 36768732, 2023). "Millon and other noted the overexpressed MDM2 mRNA and a significant decrease in MDM expression in an advanced T stage in tumour samples with HNSCC." (PMID 36551770, 2022). "The normalized MDM2 signal was amplified in the EVs isolated from RL tumour compared to those isolated from paired NAT (mean MDM2 signal ISH: NAT EVs = 2.55 ± sd 1.23, tumour EVs = 31.96 ± sd 12.4; p = 0.0059)." (PMID 36043432, 2022). "We then quantified the signal of MDM2 in the EVs isolated from different RL tumours and compared this signal to that of paired NAT EV for these same tumours using ImageJ software." (PMID 36043432, 2022). "In contrast, RNA-binding to the C-terminal RING domain of MDM2 can stabilize MDM2 protein; for example, we have found that binding of XIAP IRES mRNA to MDM2 stabilizes the protein and leads to increased tumor-cell survival." (PMID 36505784, 2022). "But it is undeniable that there is a strong positive correlation between the expression of MDM2 and CD8+ T cells in the tumor microenvironment." (PMID 35911966, 2022). "Collectively, these findings indicate that in vivo targeting of MDM2 by MX69 sensitizes chemo-resistant MM cells to BTZ treatment, induces apoptosis in MM cells and suppresses MM tumor growth." (PMID 35326742, 2022). "Tumor cells are positive for CDK4 (left) and MDM2 (right encircled shows nuclear positivity for MDM2)." (PMID 36093467, 2022). "MDM2 was also reported to mediate HUWE1 degradation and in turn regulate the abundance of Mcl1 and PP5 to contribute to tumor cell drug resistance." (PMID 35937685, 2022).
tumor (continued). "In tumor cells, FOXO3 protein binds to circFOXO3, inhibiting the binding of FOXO3 to E3 ubiquitin-protein ligase MDM2 (MDM2), and promoting the enrichment of FOXO3 protein, thereby inducing tumor cell apoptosis." (PMID 36344492, 2022). "It has been shown that TRIM28 not only associates with MAGE-C2 but also enhances the E3 ligase activity of MDM2, which implied that TRIM28 is possibly involved in blocking the tumor suppression of MGAE-C2." (PMID 35927984, 2022). "Immunohistochemical studies using primary antibodies for MDM2 (clone SMP14, Zeta, dilution 1/230) and CDK4 (clone DCS-31, Zeta, dilution 1/230) revealed that the tumor cells in both components were immunoreactive for CDK4." (PMID 34089125, 2022). "MDM2 and TG2 inhibitors, as well as ferroptosis activators, are able to inhibit tumor cell growth in pre-clinical models of RCC, but future clinical studies are needed to validate their anticancer activities." (PMID 35892875, 2022). "Increased proliferative capacity as well as expression of important factors for tumor growth and angiogenesis including Bcl-2, phosphorylated proteins ERK1/2, CXCR4, VEGF, and MDM2 mRNA was seen in those implanting with both MSC-EXOs and tumor cells." (PMID 36117723, 2022). "An increase in the MDM2 and CDK2 genes that are located on chromosome 12 is a distinguishing feature of the tumour." (PMID 36176865, 2022). "In summary, we have not demonstrated that a change in expression profiles of CDKN2A, MDM2, E2F2 and LTF genes in tumour and margin tissues has a significant impact on the pathogenesis of OSCC." (PMID 36551770, 2022). "significantly increased expression of TRIB2 in tumor tissue correlates with increased phosphorylation of AKT, FOXO3a, MDM2 and impaired treatment response." (PMID 36300089, 2022). "Most notably, we found that CCND1 and CCND2 were significantly downregulated upon PAIP1 knockdown in SMMC-7721 xenograft tumor cells, suggesting that PAIP1 promotes CCND1, CCND2, and MDM2 expression in HCC cells." (PMID 36436074, 2022). "While still entirely hypothetical, characterizing patterns of iatrogenic tumor evolution are minimally described to date in DDLPS, and this would be potentially useful when thinking about the implications of MDM2 inhibition." (PMID 36439412, 2022). "Then, we found that MDM2 was significantly downregulated upon PAIP1 knockdown in SMMC-7721 xenograft tumor cells, suggesting that PAIP1 promotes MDM2 expression in HCC cells." (PMID 36436074, 2022).
tumor (continued). "Previous studies identified SP-141 as a potent MDM2 inhibitor (Ki = 28 nM) based on SAR studies and its anti-tumor activity in multiple human tumor xenografts, including MCF-7 and HepG2." (PMID 33924734, 2021). "The expression of CDH2, MDM2 and TNFSF10 was significantly upregulated in tumor tissue, while expression of PAX8 and FERMT2 was significantly downregulated." (PMID 33850477, 2021). "The palbociclib and RG7388 (MDM2 inhibitor) combination in DDL led to an increased rate of apoptosis, recued tumor growth and had a significant increase in median PFS compared to a single agent alone." (PMID 34362013, 2021). "Although tumours with gene amplification and overexpressing MDM2 and MDM4, the negative regulators of p5330,31, are obvious candidates for such therapy, other tumours should be targetable with this type of compound." (PMID 34711913, 2021). "It is over-expressed in some cancer types including, prostate, bladder, and colon and exerts its oncogenic or tumor suppressor functions largely via ubiquitination of proteins with tumor suppressor or oncogenic activities such as PTEN, MDM2, AKT, Myc and Ras." (PMID 33962630, 2021).